INS (insulin)
Diseases named in the same sentence as INS in open-access papers (continued):
Sharing a sentence is not in itself a finding about the gene and the disease.
Hypoglycemia (continued). "Further research is needed to examine the physiological mechanisms underlying the relationship between fasting and balance including the role of energy regulating hormones (insulin, leptin, adiponectin, ghrelin) as well as the resulting metabolic and biochemical changes (e.g., hypoglycemia)." (PMID 20388217, 2010). "A retrospective study in neurosurgery patients has shown that 6 to 70% of the intravenous insulin dose, administered by the subcutaneous route, provided satisfactory glucose control with no increase in risk of hypoglycemia." (PMID 20840773, 2010). "In view of the decreased fetal plasma insulin levels observed in the high altitude fetus, it is worth noting the decrease in pancreatic β cell mass and function which accompany hypoglycemia-associated fetal growth restriction in fetal sheep." (PMID 20049329, 2010). "The major side effect of intensive insulin therapy is hypoglycemia." (PMID 22022208, 2010). "In these three trials, colesevelam did not significantly increase the risk of hypoglycaemia when added to existing metformin-, sulfonylurea- or insulin-based therapy in patients with T2DM." (PMID 20415686, 2010). "Therefore, a separate pooled analysis of hypoglycemia was conducted in which confounding effects of a sulfonylurea or insulin as either background or comparator therapy were removed." (PMID 20412573, 2010). "Likewise, basal insulin analogue trials exhibit significantly lower risks of nocturnal hypoglycemia with glargine (P = .00003) and detemir (P < .00001) relative to NPH." (PMID 20589066, 2010). "The hypoglycemia is due to a sudden outpouring of insulin from dying beta cells." (PMID 21234414, 2010). "In some cases, progression from asymptomatic to hypoglycemia requiring oral medication or insulin may happen quickly." (PMID 20587063, 2010). "Our preliminary data showing that preventing ROS production during insulin-induced hypoglycemia prevents the subsequent development of HAAF provide further support for this hypothesis." (PMID 22022208, 2010). "Interestingly, Levin and colleagues did find that falls in VMH glucose concentration in response to insulin-induced hypoglycemia were correlated with increased food intake." (PMID 22022208, 2010). "Interestingly, in forced titration studies where people are treated to a glucose target, glucose control tends to be similar between NPH insulin and insulin glargine, but hypoglycaemia rates are very different (by ∼40%)." (PMID 20946269, 2010). "It controls the blood glucose concentration and can restore glucose-stimulated insulin secretion without excess risk of hypoglycemia." (PMID 20582183, 2010). "Thus, in the present study, we investigate the potential bias associated with measurement technique, heart rate correction, and type of insulin when measuring the QTc during hypoglycemia." (PMID 21234404, 2010). "However, in healthy humans, plasma ghrelin concentrations are decreased during insulin-induced hypoglycemia, suggesting species-specific differences between rodents and humans." (PMID 20798765, 2010). "Hypoglycemia may reflect an additive effect in the NOD mouse of exogenous insulin and temporarily continuing β-cell replication in a glucose-resistant fashion." (PMID 19287497, 2009). "Our results revealed a much wider variation in blood insulin values compared to variation in blood glucose levels, suggesting that the effects of exposure are secondary to hyperinsulinemia, and to a lesser degree, to hypoglycemia." (PMID 19893948, 2009). "Furthermore, an in vivo investigation showed that except for fasting, GK expression is up-regulated in rat models (antecedent insulin-induced hypoglycaemia and diet-induced obesity) with defective glucosensing." (PMID 19442093, 2009).
Hypoglycemia (continued). "This study also demonstrated another important issue: there is a reverse relationship between C-peptide levels (endogenous indicator of insulin secretion) chronic complications - that is, the higher the C-peptide levels, the lower the incidence of nephropathy, retinopathy and hypoglycemia." (PMID 19835616, 2009). "Nateglinide may exert a more physiologic effect on insulin secretion – i.e. a glycemia-dependent response – than repaglinide, presenting less propensity to elicit hypoglycemia in vivo." (PMID 19619327, 2009). "In addition, hypoglycemia induced by T. chebula is probably mediated through enhanced secretion of insulin from the beta-cells of the pancreatic islets or through an extra pancreatic mechanism." (PMID 19835614, 2009). "Another potential criticism of this analysis is that it does not account any insulin specific effects outside of change in HbA1c and risk of hypoglycaemia." (PMID 19804622, 2009). "One possible explanation, thus, is that intensive glucose control has time-limited positive homodynamic effects (up to some days), and that afterward the positive effects of intensive insulin treatment are concealed by a higher complication rate related to adverse events, especially hypoglycemia." (PMID 20003200, 2009). "His insulin level measured during an episode of hypoglycemia was undetectable." (PMID 19689813, 2009). "C-Peptide assays are used in a large variety of studies, for example:on liver metabolism, on ketoacidosis, in looking at infants of insulin-treateddiabetic mothers, in insulin-induced hypoglycemia, during oral glucosetolerance test, or in comparing portal and peripheral blood." (PMID 18509495, 2008). "For example, a replaced version of an optimal insulin injection procedure is usedby the advisory mode, where the mode recommends reducing the amount of NPHinsulin from 10 to 6 U before dinner resulting in avoiding hypoglycemia duringbedtime." (PMID 18566688, 2008). "She couldn’t reduce the amount of insulin fast enough to keep it within an acceptable range and needed to give him sugar pills to prevent hypoglycemia." (PMID 18568931, 2008). "Thus, it is apparent that various insulin regimens, including insulin monotherapy, are effective for attaining glycemic control, but the rates of adverse outcomes such as hypoglycemia and weight gain vary with the different regimens." (PMID 19902051, 2008). "An insignificant increase of nocturnal hypoglycemia during the time interval t1 in the breakfast group could be due to incorrect adjustments of premeal insulin during dinner since this time interval corresponds to post meal." (PMID 21318060, 2008). "Then the insulin dose is decreased by 50% or to the degree that maintains glycemic control without causing hypoglycemia." (PMID 18279520, 2008). "There is noexplanation about this direction because it is believed that the emergence oflong-term in vivo sensors should enhance the blood glucose measurement andconsequently ease the predictions and plans for the insulin therapies to avoidboth hyper- and hypoglycemia." (PMID 18437199, 2008). "Apparently, glucose must be co-infused to prevent and correct insulin-induced hypoglycaemia." (PMID 18680584, 2008). "Also, Davidson and coworkers reported experiences with a computer-directed intravenous insulin system that resulted in rapid glycaemic control and a low incidence (2.6 %) of hypoglycaemia in a large patient cohort." (PMID 18205930, 2008). "Comparative analysis amongst various insulin regimens shows that combination of metformin, and glimeperide with SC administration of basal insulin Lantus required the least daily dose of insulin with least consequential hypoglycemia as well as weight gain." (PMID 19902051, 2008). "Treatments that elevate insulin concentrations in the blood independent of the ambient glucose inevitably carry risk of intermittent hypoglycaemia." (PMID 18215172, 2008).
Hypoglycemia (continued). "However, this increases the likelihood of hypoglycaemia, which is the most frequent and most feared side effect of insulin treatment and is a limiting factor to improving glucose control." (PMID 18489577, 2008). "Hypoglycaemia rates are slightly higher when SUs are retained in the oral regimen, and best results seem to occur when these are replaced by using slightly higher starting doses of the basal insulin." (PMID 18215172, 2008). "The reason that IIT may result in increased mortality is unclear but may be related to a direct effect of insulin or to insulin-induced hypoglycemia." (PMID 18312617, 2008). "Hyperinsulinemic hypoglycemia occurs due to insulin hypersecretion by the islets of Langerhans." (PMID 19893643, 2008). "While imperfect insulin replacement places the patient at increased risk for frequent hypoglycemia, patients with T1DM also suffer from compromised counterregulatory responses to hypoglycemia." (PMID 17326722, 2007). "However, since higher plasma insulin levels result in hypoglycemia and hypoglycemia is detrimental to brain function, peripheral insulin resistance develops to maintain higher plasma glucose." (PMID 17437648, 2007). "The authors reported that this may have been due to reluctance of the investigators and/or subjects to intensively titrate the insulin dose likely because of fear of hypoglycaemia or weight gain." (PMID 17997807, 2007). "Since nitric oxide is very unstable, insulin secretion stimulated by nitric oxide would be transient and may avoid hypoglycemia as observed by constitutive secretion of insulin from engineered cells." (PMID 17941991, 2007). "Because insulin kinetics are linear using logarithmic transformation, Shibutani and Ogawa suggested that duration of the subsequent hypoglycaemia and the required glucose administration could easily be determined." (PMID 17963523, 2007). "For example, if hypoglycemia is detected in an inpatient, this might indicate an adverse event (mismanagement of insulin treatment)." (PMID 17472749, 2007). "The mechanisms behind gastric discomfort and fatigue are not fully understood, but the rapid shift in glucose and insulin concentrations, relative hypoinsulinaemia and hypoglycaemia may contribute to such symptoms." (PMID 17894830, 2007). "Although NPH may have efficacy in achieving glycemic control that is comparable to long-acting insulin analogs, direct comparison trials have shown that rates of overall and nocturnal hypoglycemia are lower with insulin analogs." (PMID 17448241, 2007). "While there appears to be some benefit of testing for those on insulin to avoid hypoglycemia, the little evidence associating SMBG with better glycemic control in patients not on insulin is weak and conflicting." (PMID 17164006, 2006). "Previous studies have shown that intravenous (IV) insulin administration improves cognition in AD patients, but IV insulin is not a viable therapeutic option due to the risk of hypoglycemia." (PMID 16956414, 2006). "The hypoglycaemia that occurs in NICTH is not dependent on endogenous insulin secretion, but instead is caused by tumour production of a prohormone form of IGF-II." (PMID 16942396, 2006). "In the investigation of spontaneous hypoglycaemia, it is important to document hypoglycaemia with a reliable laboratory blood glucose measurement and to take blood at the time of hypoglycaemia for measurement of insulin, C-peptide, and other hormones before treatment with glucose has been given." (PMID 16942396, 2006). "aIf hypoglycemia is present at 3:00 a.m., reduce the 10:00 p.m. insulin dose." (PMID 15916471, 2005). "Biochemical evaluation confirmed hypoglycemia and abnormally high levels of insulin." (PMID 15543375, 2004). "Thus, steroids, epinephrine, and glucagon appear to facilitate recovery from insulin-induced hypoglycaemia in a manner distinct from, but complementary to, the molecular clock." (PMID 15523558, 2004).
Hypoglycemia (continued). "Further, the presentfindings suggest that nateglinide may exert a morephysiologic effect on insulin secretion than comparatoragents and thereby have less propensity toelicit hypoglycemia in vivo." (PMID 12369728, 2001). "However, reports of hypoglycemia—especially in patients previously on insulin—suggest that modulators may also alter glucagon secretion, raising the risk of hypoglycemia in CFRD." (PMID 41552835, 2026). "However, while subgroup analyses by type of weekly insulin were consistent with the overall analysis, those by type of daily insulin revealed that the incidence rate of hypoglycaemia with weekly insulins was similar to degludec and higher compared to glargine U100." (PMID 41048193, 2026). "High doses of insulin were used with caution, as concern remained that bound insulin might later dissociate and cause severe hypoglycemia; however, this did not occur." (PMID 41472947, 2026). "Due to the efficacy in reducing HbA1c, accompanied by a weight loss effect, low risk of hypoglycemia, and ease of use (simple titration plan and once-daily or even once-weekly administration), the ADA/EASD Guideline recommends to preferentially use GLP-1 RAs in T2D patients before insulin therapy." (PMID 40870388, 2025). "For unplanned activity, AID systems may provide some protection against exercise-induced hypoglycaemia relative to other insulin delivery modalities when basal insulin delivery is fixed, but CHO intake is typically required, and to a greater extent, compared with planned activity." (PMID 39653802, 2025). "Combination therapy with a GLP-1 RA plus basal insulin has been reported to be highly effective in reducing HbA1c and preventing weight gain associated with insulin therapy, without increasing the risk of hypoglycemia." (PMID 41012462, 2025). "Interestingly, during hypoglycemia, insulin detemir demonstrated higher glycemic thresholds for adrenergic symptoms and greater maximal responses to both adrenergic and neuroglycopenic symptoms compared to regular insulin, but it also caused earlier and more severe impairment of cognitive function." (PMID 40023730, 2025). "The risk of hypoglycemia is low, particularly in patients not using insulin or sulfonylureas." (PMID 39917155, 2025). "In the case of the identification of insulin-mediated hypoglycemia, the evaluation of pancreatic neuroendocrine tumors (P-NETs), which represent the most common and worrisome causes of non-diabetic insulin-mediated hypoglycemia, must be considered." (PMID 39941267, 2025). "This increased risk for hypoglycemia might be due to a lack of storage in combination with high insulin levels, which predisposes patients to hypoglycemia." (PMID 39913386, 2025). "Glucose serves as the primary energy substrate for the brain, and alterations of carbohydrate metabolism (such as insulin resistance, abnormal neuronal glucose uptake, recurrent hypoglycemia, and cerebrovascular hypoperfusion) may disrupt neuronal integrity and synaptic function." (PMID 41146776, 2025). "Furthermore, our patient’s poor understanding of the disease and the principles of insulin dosing (including episodes of hypoglycemia), as well as a history of alcohol misuse, would make insulin pump use questionable and require additional training and support." (PMID 41471899, 2025). "Additionally, the risk of hypoglycemia, weight gain, injection site reactions, and lack of physiologic insulin delivery patterns continue to impact patient quality of life and treatment satisfaction." (PMID 41531706, 2025). "Additionally, our institution’s protocol mandates a blood glucose check before insulin administration, which might have lowered the rate of hypoglycemia reported with insulin use." (PMID 40901501, 2025). "However, the second component of DKA treatment, intravenous insulin, led to hypoglycemia which would have caused significant morbidity had it not been recognized." (PMID 41393585, 2025).
Hypoglycemia (continued). "Metabolic profile of adenine-diet induced CKD cardiomyopathy was characterised by reduced exogenous glucose supply due to circulating hypoglycaemia and hypoinsulinaemia which could be responsible for reduced expression of insulin-responsive myocardial glucose transporter GLUT4." (PMID 41272152, 2025). "Similarly, elderly participants (mean age 76 +/− 6 years) in another cohort study with positive stimulated C‐peptide and recorded hypoglycaemia on continuous glucose monitoring underwent simplification of their insulin regime with the substitution of prandial insulin using other non‐insulin therapy." (PMID 39797595, 2025). "For example, an interferent that causes a false elevation in the glucose reading may result in the patient undergoing unnecessary corrective treatment with insulin, which may result in hypoglycemia (e.g., after absorption of mannose and/or galactose from food)." (PMID 40218498, 2025). "However, there still exists a potential risk of nocturnal hypoglycemia, especially if the insulin dose is not well-calibrated." (PMID 40190894, 2025). "Additionally, since hypoglycemia may result from improper insulin dosing, categorizing them into insulin-induced and non-insulin-induced could be beneficial." (PMID 40150028, 2025). "The advantage offered by AHCL systems persists even during school hours, which are often subject to unexpected reductions in insulin doses for those using MDI in order to reduce the risk of hypoglycemia, particularly in cases where there is no cooperation from the school." (PMID 41464483, 2025). "However, individuals using insulin pumps experienced a reduction in severe hypoglycemia." (PMID 41146752, 2025). "Earlier studies have established that intensive insulin therapy has no significant benefits in critically ill patients, whether septic or not, and poses a greater risk for hypoglycemia." (PMID 39838305, 2025). "However, several analysts question whether this adoption will effectively address challenges related to insulin use, such as insulin shortages, refrigeration/equipment limitations, and hypoglycemia, among other challenges in these countries." (PMID 40245017, 2025). "In conclusion, this non-randomized clinical trial demonstrates that a short-term low-carbohydrate diet significantly improves glycemic variability and reduces insulin requirements in hospitalized patients with insulin-deficient diabetes, without increasing the risk of hypoglycemia or ketoacidosis." (PMID 41586239, 2025). "Importantly, GLP-1RA have a lower risk of hypoglycemia with treatment or without sulfonylureas or insulin." (PMID 40612440, 2025). "Importantly, because this mechanism is independent of insulin, the risk of hypoglycemia is minimal unless combined with insulin or insulin secretagogues." (PMID 40863154, 2025). "Importantly, lethality in malaria-infected adrenalectomized mice was associated with hypoglycemia, which was independent of insulin and TNF-α." (PMID 40702267, 2025). "Once delivered, a child cannot quickly reduce insulin secretion, which may cause fetal hypoglycemia." (PMID 39832134, 2025). "Patients may forget whether they have taken their medication, e.g. insulin, or not, which can cause both hyper- and hypoglycemia and which in turn can further impair cognitive abilities and increase the risk of other diabetic complications." (PMID 39876043, 2025). "To determine whether the changes in gut flora can impact specific nervous system functions before puberty, we tested the effect of maternal antibiotic use on a well characterized reflex arc in their offspring—epinephrine release in response to insulin-induced hypoglycemia." (PMID 40693139, 2025). "Insulin and sulfonylureas should not be regarded as CV-risk–based therapeutic choices due to their higher risk of hypoglycemia, although they may still be required for glycemic control when other options are insufficient or unavailable." (PMID 41299307, 2025).